SLC7A7 (solute carrier family 7 member 7)
Diseases named in the same sentence as SLC7A7 in open-access papers (continued):
Sharing a sentence is not in itself a finding about the gene and the disease.
osteoporosis (3 papers, 2020 to 2023). A condition of reduced bone mass, with decreased cortical thickness and a decrease in the number and size of the trabeculae of cancellous bone (but normal chemical composition), resulting in increased fracture incidence. "Postnatal growth failure, delayed skeletal development and reduced survival prevent studies of bone mineralization and osteoporosis in skeletally mature mice with Slc7a7 deficiency; therefore, we generated a conditional Slc7a7 mouse model." (PMID 37486182, 2023). "The expression level of SLC7A7 is high in intestine and kidney but low in skeletal muscle, and the mutation of SLC7A7 gene usually induces many complications, such as persistent hypotonia, birth retardation, osteoporosis, coma and mental development disorder." (PMID 35054897, 2022). "Given that recent in vitro studies have implicated Slc7a7 in osteoblast differentiation, we hypothesized that Slc7a7 deficiency in osteoblasts might cause osteoporosis." (PMID 37486182, 2023). "Hence, we developed a global Slc7a7 knockout mouse model (Slc7a7Lbu/Lbu) and a conditional Slc7a7 knockout mouse model (Slc7a7f/f) to further investigate aspects of growth failure, skeletal defects and osteoporosis associated with Slc7a7 deficiency." (PMID 37486182, 2023). "Regardless, future in vivo studies utilizing tissue-specific and developmental stage-specific Slc7a7 knockout mouse models will advance our understanding of potential cell-autonomous or non-cell-autonomous mechanisms underlying growth failure, delayed skeletal development and osteoporosis in LPI." (PMID 37486182, 2023). "Given the growth failure and delayed skeletal development in Slc7a7Lbu/Lbu mice and the role of Slc7a7 in osteoblast differentiation in cell studies, we hypothesized that loss of Slc7a7 in osteoblasts might impair growth and skeletal development and contribute to osteoporosis in LPI." (PMID 37486182, 2023). "Thus, our data suggest that Slc7a7 deficiency in osteoblasts does not contribute to the growth failure, delayed skeletal development or osteoporosis phenotypes in LPI." (PMID 37486182, 2023).
osteosarcoma (3 papers, 2020 to 2026). A usually aggressive malignant bone-forming mesenchymal neoplasm, predominantly affecting adolescents and young adults. "Our study pointed out that the expression of SLC7A7 is significantly associated with the prognosis of osteosarcoma." (PMID 36119478, 2022). "Our study showed that the expression level of SLC7A7 was significantly decreased in osteosarcoma groups based on Western blot results." (PMID 36119478, 2022). "We speculated that the proliferation and migration of osteosarcoma cells can down-regulate their SLC7A7 expression." (PMID 36119478, 2022). "However, the role of SLC7A7 in osteosarcoma progression and immunology is still unclear." (PMID 36119478, 2022). "Five of the seven immune-related genes (CDCA7, GZMA, SLC7A7, VAMP8, and EVI2B) were highly expressed in the osteosarcoma group, while two of these immune-related genes (IFITM3 and ACTA2) were lowly expressed." (PMID 33384961, 2020). "Results showed that the expression levels of SLC7A7 and ACSS2 were significantly decreased in two osteosarcoma cell groups (U20S and 143B) compared with the osteoblast cell group (hFOB), whereas MYC was up-regulated in osteosarcoma groups." (PMID 36119478, 2022). "The heatmap of these seven immune-related genes expression level in GSE42352 indicated that five of these genes (CDCA7, GZMA, SLC7A7, VAMP8, and EVI2B) were highly expressed in the osteosarcoma group, but two of these genes (IFITM3 and ACTA2) were highly expressed in the normal group." (PMID 33384961, 2020).
ovarian carcinoma (3 papers, 2020 to 2022). A malignant neoplasm originating from the surface ovarian epithelium. "Besides, SLC7A7 has been highly expressed in chemotherapy-resistant ovarian cancer and is associated with chemotherapy outcomes." (PMID 36119478, 2022). "A total of 10 overlapped genes (SLC7A7, SLC7A8, COL4A5, etc.)and one metabolite (L-threonine) were significantly correlated with the pathway of protein digestion and absorption in ovarian cancer." (PMID 34539736, 2021).
anemia (2 papers, 2025). A reduction in the number of red blood cells, the amount of hemoglobin, and/or the volume of packed red blood cells. "Different lines of evidence underscore the pivotal role of Slc7a7 in the regulation of hematopoietic processes, as LPI patients often present with chronic microcytic normochromic anemia, which suggests disruptions in iron metabolism and impaired hemoglobin synthesis." (PMID 39881295, 2025).
atherosclerosis (2 papers, 2023 to 2025). A disease characterized by the build-up of fatty material and calcium deposition in the arterial wall resulting in partial or complete occlusion of the arterial lumen. "Next, we explored the potential of folate and glutamine as PET tracers, leveraging high expression of folate receptor (Folr2) and solute carrier family 7 member 7 (Slc7a7), respectively, in atherosclerosis-associated macrophages." (PMID 41206594, 2025).
colorectal cancer (2 papers, 2024 to 2025). A primary or metastatic malignant neoplasm that affects the colon or rectum. "And SLC7A7 is enriched during the EMT process and may facilitate colorectal cancer metastases through the SLC7A7/APC/WNT/β‐catenin signaling pathway." (PMID 41176774, 2025). "In colorectal cancer (CRC), SLC7A7 appears to play a role, but the features and mechanisms are not yet well understood." (PMID 39730571, 2024).
Fanconi syndrome (2 papers, 2023 to 2024). "Although the clinical manifestations in our patient were characterized by RTA/Fanconi syndrome with rickets, the patient also harbored a homozygous nonsense variant of SLC7A7." (PMID 37927490, 2023).
hemophagocytic lymphohistiocytosis (2 papers, 2017 to 2018). "Although SLC7A7 gene expression is enhanced by GM-CSF, AM differentiation is not impaired in LPI patients, and GM-CSF appears to be inefficient or even dangerous in hemophagocytic-lymphohistiocytosis (HLH) related to LPI." (PMID 28057010, 2017). "In this context, the clinical features resembling hemophagocytic lymphohistiocytosis (HLH) in LPI could be, hence, ascribed to a spontaneous and persistent activation of macrophages consequent to the lack of a functional SLC7A7/y+LAT1 in these cells." (PMID 29616026, 2018).
hepatocellular carcinoma (2 papers, 2025). A malignant tumor that arises from hepatocytes. "SLC7A7 is a key intermediary factor in the ATF3-SLC7A7 axis that regulates mTORC1 signaling to attenuate lipogenesis in hepatocellular carcinoma." (PMID 40362725, 2025).
melanoma (2 papers, 2021 to 2023). A malignant, usually aggressive tumor composed of atypical, neoplastic melanocytes. "We found that SLC7A7 expression was significantly higher in brain and CNS, breast, colorectal, esophageal, gastric, head and neck, leukemia, lymphoma, melanoma and pancreatic cancers, compared to the normal tissues." (PMID 33632211, 2021).
multiple myeloma (2 papers, 2014 to 2021). "Multiple myeloma and breast cancer were exceptions where high SLC7A7 expression showed a better prognosis." (PMID 33632211, 2021). "The expression profiles of SLC7A7, together with CSGAL-NACT1, were used to stratify multiple myeloma patients into two groups with different prognoses." (PMID 33632211, 2021).
pancreatic cancer (2 papers, 2021 to 2025). "The results showed that OLR1 and SLC7A7 were highly expressed in pancreatic cancer patients and associated with the disease stage, indicating that OLR1 and SLC7A7 were important for the diagnosis of pancreatic cancer." (PMID 41176774, 2025). "Further studies are needed to investigate the correlation of OLR1 and SLC7A7 with pathological staging and survival in pancreatic cancer patients through immunohistochemistry." (PMID 41176774, 2025). "Furthermore, we analyzed the expression levels of OLR1 and SLC7A7 in pancreatic cancer patients using the GPEIA2." (PMID 41176774, 2025). "However, there are very few reports on the roles of OLR1 and SLC7A7 in pancreatic cancer liver metastases." (PMID 41176774, 2025). "We will construct pancreatic cancer liver metastases models in mice using SLC7A7 and OLR1 knockout pancreatic cancer cells to verify their crucial roles in pancreatic cancer liver metastases." (PMID 41176774, 2025). "The marker genes OLR1 and SLC7A7, which were significantly upregulated in LEMS, were validated in clinical samples, suggesting their potential as biomarkers for pancreatic cancer liver metastases." (PMID 41176774, 2025).
periodontitis (2 papers, 2023 to 2024). An acute or chronic inflammatory process that affects the tissues that surround and support the teeth. "Results of our study discovered that the most significant crosstalk genes between periodontitis and MS were FAM46C, SLC7A7, LY96, CFI, DDIT4L, CD14, and IGJ, which may be associated with response to molecules of bacterial origin." (PMID 38218802, 2024). "Venn diagrams revealed that there were eight shared genes (FAM46C, SLC7A7, LY96, CFI, DDIT4L, CD14, C5AR1, and IGJ) that overlapped between periodontitis and MS which were screened by WGCNA and DEGs." (PMID 38218802, 2024).
renal failure (2 papers, 2019 to 2021). "Additional studies at longer periods of time after y+LAT1 ablation will be necessary to assess whether Slc7a7−/− mice develop renal insufficiency." (PMID 31653080, 2019).
asthma (1 paper, 2015). "Furthermore, based on described biological functions, it is reasonable to suppose that genes which are potentially associated with asthma symptoms may be located in this region, with the example of SLC7A7, MMP14 and DAD1." (PMID 26635092, 2015). "The SLC7A7 gene is involved in the macrophage differentiation process and its involvement in asthma pathogenesis has been described." (PMID 26635092, 2015).
breast carcinoma (1 paper, 2021). "Another cohort (GSE1456) including 159 samples showed that SLC7A7 expression was associated with a worse prognosis in breast cancer (relapse-free survival [RFS]; HR = 2.32, 95% CI 1.05–5.14, P = 0.0375)." (PMID 33632211, 2021). "Interestingly, one cohort (GSE19615) including 115 samples showed that high SLC7A7 expression was associated with a better prognosis in breast cancer (distant metastasis-free survival [DMFS]; HR = 0.19, 95% CI 0.06–0.68, P = 0.0103)." (PMID 33632211, 2021).
breast invasive carcinoma (1 paper, 2021). "The results indicated that the expression levels of SLC7A7 were significantly increased in BRCA (breast invasive carcinoma), CHOL (cholangiocarcinoma), ESCA (esophageal carcinoma), HNSC (head and neck squamous cell carcinoma) and STAD (stomach adenocarcinoma), compared to adjacent control samples." (PMID 33632211, 2021).
Carditis (1 paper, 2024). "Targeting SLC7A7 may have adverse effects on the circulatory system (Carditis) and congenital anomalies (Cardiac shunt/ heart septal defect), while it may be beneficial for infectious diseases (Herpes zoster) and sense organs (Keratoconus) and sense organs (Keratoconus)." (PMID 39734218, 2024).
colon cancer (1 paper, 2024). "We analyzed the changes in SLC7A7 and gene mutations, acquisitions, and deletions in colon cancer, the difference in APC, TTN, KRAS, SYNE1, RYR2, and LRP1 mutations was statistically significant." (PMID 39730571, 2024). "In colon cancer, the SLC7A7 Somatic Mutation Rate: is 1.23%." (PMID 39730571, 2024). "Methylation was negatively correlated with SLC7A7 expression in several tumors, including colon cancer." (PMID 39730571, 2024). "SLC7A7 activation of the Wnt/β-catenin signaling pathway promotes colon cancer progression through the EMT process and m7g modification promotes SLC7A7 mRNA stabilization." (PMID 39730571, 2024). "Single-cell sequencing results of colon cancer tissues were analyzed, and the vast majority of SLC7A7 was expressed in macrophages." (PMID 39730571, 2024).
creatine deficiency syndrome (1 paper, 2014). "For example, SLC6A8, which is linked to a creatine deficiency syndrome that causes mental retardation, severe speech delay, and seizures, and SLC7A7, which causes lysinuric protein intolerance are both missing in birds (OMIM), but have closely related paralogs that could provide compensation." (PMID 25518852, 2014).
cystinuria (1 paper, 2025). Cystinuria is a renal tubular amino acid transport disorder characterized by recurrent formation of kidneys cystine stones. "In contrast to cystinuria, the mutation was identified exclusively in the light subunit SLC7A7 (chromosomal locus 14q11.2), which mediates the transport of dibasic amino acids from the intracellular to the basolateral compartment." (PMID 41142409, 2025).
esophageal squamous cell carcinoma (1 paper, 2024). Esophageal squamous cell carcinoma (ESCC) is a type of esophageal carcinoma (EC) that can affect any part of the esophagus, but is usually located in the upper or middle third. "In esophageal squamous cell carcinoma, SLC7A7 is highly expressed in tumor tissues and patients have a poor prognosis." (PMID 39730571, 2024).
gout (1 paper, 2024). A condition characterized by painful swelling of the joints, which is caused by deposition of urate crystals. "By PPI analysis we found evidence based on experimental determined that the identified gout causal gene SLC7A7 was strongly correlated with the targets SLC22A6 and SLC22A8 of probenecid." (PMID 39734218, 2024). "18, 95% CI: 0.03–0.34, P = 0.022) and cg16465430 (β = 0.07, 95% CI: 0.00-0.14, P = 0.048), located in the SLC7A7 gene region, was linked to increased gout risk." (PMID 39734218, 2024). "In the druggability assessment, SLC7A7 and FCGR2B were validated, and both were significantly associated with relevant targets of the currently commercially available gout drugs Probenecid and Rilonacept, respectively." (PMID 39734218, 2024). "Ultimately, eight genes were identified as possible drug targets in gout, including three risk genes (ALDH3B1, NRBP1, SUMF1) and three protective genes (FCGR2B, RCE1, SLC7A7)." (PMID 39734218, 2024). "In druggability evaluation, we found that SLC7A7 may have greater potential for gout drug development, whereas targeting NRBP1 needs to be carefully considered." (PMID 39734218, 2024). "Eight potential therapeutic targets (ALDH3B1, FCGR2B, IL2RB, NRBP1, RCE1, SLC7A7, SUMF1, THBS3) for gout were identified in the discovery cohort using MR analysis." (PMID 39734218, 2024).
Hypertension (1 paper, 2025). The presence of chronic increased pressure in the systemic arterial system. "Prior research has established a strong association between the Slc7a7 gene and human longevity and hypertension." (PMID 40227207, 2025).
kidney chromophobe (1 paper, 2021). "However, SLC7A7 expression was significantly lower in KICH (kidney chromophobe), KIRC (kidney renal clear cell carcinoma), KIRP (kidney renal papillary cell carcinoma), LIHC (liver hepatocellular carcinoma), LUAD (lung adenocarcinoma) and LUSC (lung squamous cell carcinoma) than in normal controls." (PMID 33632211, 2021).
metastatic melanoma (1 paper, 2022). A melanoma that has spread from its primary site to another anatomic site. "Furthermore, although high expression of most amino acid transporters was correlated with increased mortality, elevated expression of SLC38A1 (glutamine transporter) and SLC7A7 (lysine transporter) had strong benefits for patients with metastatic melanoma." (PMID 36457136, 2022).
prostate adenocarcinoma (1 paper, 2024). "Meanwhile, high SLC7A7 expression levels were associated with short disease-free survival in LGG, STAD, UVM, and Prostate adenocarcinoma (PRAD)." (PMID 39730571, 2024).
pulmonary alveolar proteinosis (1 paper, 2019). A rare lung disorder characterized by the filling of the pulmonary alveoli with proteinaceous material which stains positive with periodic acid-Schiff stain. "Slc7a7−/− mice also, like human patients, develop pulmonary alveolar proteinosis (PAP)." (PMID 31653080, 2019).
T-cell acute lymphoblastic leukemia (1 paper, 2021). Acute lymphoblastic leukemia of T-cell origin. "For T cell acute lymphoblastic leukemia, SLC7A7 inhibits cell apoptosis and promotes cell migration and invasion." (PMID 34422829, 2021).
thyroiditis (1 paper, 2018). Inflammation of the thyroid gland. "Thyroiditis was significantly correlated with SLC7A2, SLC7A3, SLC7A7, and SLC7A9." (PMID 30558624, 2018).
uveal melanoma (1 paper, 2024). A melanoma derived from melanocytes of the uveal tract. "The high expression level of SLC7A7 was associated with improved prognosis in Sarcoma (SARC) and SKCM but poor prognosis in BLGG and uveal Melanoma (UVM) as seen by survival maps." (PMID 39730571, 2024).